HOTAIRM1 (HOXA transcript antisense RNA, myeloid-specific 1)
Diseases named in the same sentence as HOTAIRM1 in open-access papers (continued):
Sharing a sentence is not in itself a finding about the gene and the disease.
neuroblastoma (2 papers, 2021 to 2022). Neuroblastoma (NB) is the most common solid, extracranial childhood tumor. "Currently, we explored the contribution of propofol in neuroblastoma cells exposed to MPP+, which was attributed to its association with HOTAIRM1 and miR-519a-3p, expanding its clinical application due to the beneficial properties of propofol." (PMID 35350655, 2022). "Treatment with MPP+ has been observed to induce apoptosis, oxidative stress, and inflammation in neuroblastoma cells, which were abolished by propofol or silencing of HOTAIRM1." (PMID 35350655, 2022). "In summary, the silencing of HOTAIRM1 exerted protective effects on neuroblastoma cells against MPP+." (PMID 35350655, 2022). "All data implied that HOTAIRM1/miR-519a-3p axis played key roles in proliferation, apoptosis, inflammation, and oxidative stress of neuroblastoma cells treated with MPP+." (PMID 35350655, 2022). "In this study, HOTAIRM1 was upregulated in neuroblastoma cells in response to MPP+ treatment, while propofol abolished this effect." (PMID 35350655, 2022). "Thereafter, our work confirmed that miR-519a-3p inhibition weakened the effects of propofol treatment or HOTAIRM1 silencing in neuroblastoma cells." (PMID 35350655, 2022). "Propofol inhibited oxidative stress and inflammation in MPP+-induced neuroblastoma cells by targeting the HOTAIRM1/miR-519a-3p axis, implying the potential protective function of propofol against oxidative damage." (PMID 35350655, 2022). "To determine its role in early DA neuron development, we knocked down HOTAIRM1 using RNAi in vitro in a human neuroblastoma cell line, and in vivo in mouse DA progenitors using a novel in utero electroporation technique." (PMID 34298885, 2021). "Importantly, the regulatory roles of propofol on proliferation, apoptosis, and inflammation in neuroblastoma cells treated with MPP+ were involved in the HOTAIRM1/miR-519a-3p axis." (PMID 35350655, 2022). "In addition, miR-519a-3p was a target of HOTAIRM1, and inhibition of miR-519a-3p abolished HOTAIRM1 silencing-induced effects on neuroblastoma cells." (PMID 35350655, 2022). "Thus, a propofol/HOTAIRM1/miR-519a-3p regulatory network was identified in regulating neuroblastoma cell injury." (PMID 35350655, 2022). "Importantly, the increase of HOTAIRM1 and the decrease of miR-519a-3p caused by MPP+ were reversed by propofol in neuroblastoma cells." (PMID 35350655, 2022). "Moreover, the HOTAIRM1/miR-519a-3p axis could be affected by propofol, and the rescue experiments indicated that propofol showed neuroprotective properties in neuroblastoma cells by regulating the HOTAIRM1/miR-519a-3p axis." (PMID 35350655, 2022). "Therefore, propofol may suppress apoptosis, inflammation, and oxidative damage in neuroblastoma cells treated with MPP+ by regulating the HOTAIRM1/miR-519a-3p axis." (PMID 35350655, 2022). "Functionally, knockdown of HOTAIRM1 abolished MPP+-induced injury neuroblastoma cells, and propofol protected against MMP+-induced neuroblastoma cell injury by repressing HOTAIRM1." (PMID 35350655, 2022). "Besides, we also elucidated whether there was a regulatory relationship among propofol, HOTAIRM1, and miR-519a-3p in MPP+-induced neuroblastoma cells." (PMID 35350655, 2022).
Type 2 diabetes (2 papers, 2021 to 2023). "Others were associated to Type 2 diabetes (CASC15, LINC01127, NUTM2B-AS1) or diabetes renal injury in T1D (HOTAIRM1)." (PMID 35058920, 2021).
allergic asthma (1 paper, 2023). A asthma with a basis in a pathological type I hypersensitivity reaction. "HOTAIRM1 and GAS5 showed similar expression behavior, higher expression levels were observed in both asthmatic phenotypes, allergic asthma, and obesity-related asthma compared with their counterparts, healthy and obese adolescents, respectively." (PMID 37047453, 2023). "Expression levels of OIP5-AS1, MZF1-AS1, HOTAIRM1, and GAS5 in whole blood from the healthy adolescent population, obese adolescents, allergic asthma adolescents, and obesity-related asthma adolescents are differently expressed." (PMID 37047453, 2023).
anaplastic thyroid cancer (1 paper, 2021). "Similarly, in anaplastic thyroid cancer (ATC), the amplification of HOTAIRM1 genome copy number increased the expression of HOTAIRM1, and drove the occurrence of ATC by inhibiting the biosynthesis of miR-144." (PMID 35087800, 2021).
asthma (1 paper, 2023). "After that, we tested the discriminative value of these lncRNAs through the area under the curve ROC analysis and interestingly found that HOTAIRM1 and GAS5 can help discriminate between any asthma phenotype of healthy and obese patients." (PMID 37047453, 2023). "However, our results suggest that HOTAIRM1, GAS5, MZF1-AS1, and OIP5-AS1 could be potential biomarkers to help clinicians accurately stratify different asthma phenotypes, which would have an indirect impact on the early diagnosis and quality of life of asthmatic patients." (PMID 37047453, 2023). "First, we found higher levels of lncRNAs: HOTAIRM1, GAS5, MZF1-AS1, and OIP5-AS1 in the allergic asthmatic and obesity-related asthma patients compared with their counterparts’ healthy adolescents and obesity without asthma adolescents, respectively." (PMID 37047453, 2023).
Autoimmunity (1 paper, 2025). The occurrence of an immune reaction against the organism's own cells or tissues. "Functional studies using immune cell-specific HOTAIRM1 knockdown in non-obese diabetic mice are warranted to investigate its impact on the development of autoimmunity." (PMID 41198985, 2025).
breast tumor (1 paper, 2025). "We next evaluated the expression of four candidate lncRNAs in 50 paired breast tumor and normal tissue samples, confirming significant downregulation of ADAMTS9-AS2, HAND2-AS1, HOTAIRM1, and MEG3 (P < 0.001)." (PMID 40350996, 2025).
diffuse large B-cell lymphoma (1 paper, 2021). "Thus, we observed a significant positive correlation between HOXB-AS1 and the immune scores of CHOL, diffuse large B-cell lymphoma (DLBC), LGG, LIHC, prostate adenocarcinoma (PRAD), and THCA, and between HOTAIRM1 and the immune scores of CHOL, LGG, LIHC, and THCA." (PMID 34805277, 2021).
esophageal carcinoma (1 paper, 2021). A primary or metastatic malignant neoplasm involving the esophagus. "For instance, the expression levels of HOTAIRM1 showed significant inter-tumor heterogeneity in esophageal carcinoma (ESCA), GBM, and kidney papillary cell carcinoma (KIRP), which are associated with very high HOTAIRM1 expression levels." (PMID 34805277, 2021).
kidney neoplasm (1 paper, 2021). A benign or malignant neoplasm affecting the kidney. "For example, recent studies have found that CDKN2B-AS1 can be used as a biomarker for poor prognosis of kidney neoplasms, DUXAP8 enhances the progression of kidney neoplasms by downregulating miR-126, and HOTAIRM1 is downregulated in kidney neoplasms and inhibits hypoxia." (PMID 35058974, 2021).
low grade glioma (1 paper, 2019). A grade I or grade II glioma arising from the central nervous system. "Of the five previously established molecular classifications, higher HOTAIRM1 expression was more frequently detected in low-grade glioma (LGG) with wild-type IDH (LGG-IDHwt) and GBM with wild-type IDH cases." (PMID 31477638, 2019).
Obesity (1 paper, 2023). Accumulation of substantial excess body fat. "In this study, we analyzed the expression levels of the lncRNAs: HOTAIRM1, GAS5, OIP5-AS1, and MZF1-AS1 from whole blood of healthy, obese, allergic asthmatic and obesity-related asthmatic adolescents through RT-qPCR." (PMID 37047453, 2023).
papillary thyroid cancer (1 paper, 2021). "The lncRNA HOTAIRM1 was reported to be downregulated in papillary thyroid cancer, significantly associated with lymph node metastasis, TNM stage and better prognosis, and suppress cell growth, invasion and migration." (PMID 34496838, 2021).
prostate carcinoma (1 paper, 2024). A carcinoma that arises from epithelial cells of the prostate gland. "For example, ACPP (PIP = 0.999) was overexpressed in prostate cancer cell lines and HOTAIRM1 (PIP = 0.999) is antisense of HOXA1 and found to be highly expressed in prostate cancer cells enhancing cell proliferation, invasion, and metastasis." (PMID 38887957, 2024).
small cell lung carcinoma (1 paper, 2018). Small cell lung cancer (SCLC) is a highly aggressive malignant neoplasm, accounting for 10-15% of lung cancer cases, characterized byrapid growth, and early metastasis. "Further analysis revealed that HOTAIRM1 expression levels were the highest in lung ADC compared with small cell lung cancer and squamous cell lung carcinoma." (PMID 29662483, 2018).
viral infection (1 paper, 2020). "However, the role of HOTAIRM1 in the development and suppression of MDSCs during viral infection remains unknown." (PMID 33328510, 2020).
tumor (56 papers, 2016 to 2025). "This hypermethylation effectively silences HOTAIRM1 expression, which is believed to be a tumor suppressor involved in the AML-associated carcinogenesis pathway." (PMID 37705098, 2023). "In the univariate Cox-regression analysis, HOTAIRM1 expression and tumor stage were revealed as the risk factors for OSCC patient prognosis." (PMID 35087800, 2021). "HOTAIRM1 expression was positively associated with immune and stromal scores and negatively associated with tumor purity." (PMID 31477638, 2019). "HOTAIRM1 silencing caused tumor suppressive effects via inhibiting cell proliferation, migration and invasion, and inducing cell apoptosis." (PMID 30376874, 2018). "Here, we found that HOTAIRM1 transcription was activated by Da0324 in GC cells, suggesting that the anti-tumor effects of Da0324 might be caused by the up-regulation of HOTAIRM1." (PMID 35711826, 2022). "HOTAIRM1 acts as a ceRNA, sponging the tumor-suppressive miR-125b, which relieves repression on RIZ1v2 and enhances HCC cell proliferation and metastasis." (PMID 40867614, 2025). "Although some lncRNAs associated with IDH1 mutations (HOTAIRM1, NCRNA00173, MIR155HG, etc.)are involved in various tumor-associated cellular processes." (PMID 38530810, 2024). "The effects of HOTAIRM1, autophagy and lenvatinib on tumor inhibit were validated in orthotopic tumor-bearing nude mouse model." (PMID 37171645, 2023). "Aberrant expression of HOTAIRM1 has been observed across various tumor types, signifying its relevance in cancer-related processes." (PMID 37705098, 2023). "Subsequently, tumor volume and weight had a significant increase under HOTAIRM1 overexpression while showed decrease under HOTAIRM1 depletion." (PMID 38012763, 2023). "The U251 cells transfected with over-HOTAIRM1, si-HOTAIRM1, or empty vector control were inoculated into nude mice, and we found that the tumor growth was facilitated in nude mice following injection with over-HOTAIRM1 than that in the control group." (PMID 38012763, 2023). "HOTAIRM1 is down‐regulated in head and neck tumors and neck, as a tumor suppressor gene, inhibits tumor cell proliferation and migration and induces apoptosis." (PMID 35920349, 2023). "Tumor exosomal HOTAIRM1 can transfer into CAFs and competitively adsorb miR-328-5p through the ceRNA mechanism, and regulate the SPON2 expression of CAFs cells, ultimately promote the progression of NSCLC." (PMID 36153414, 2022). "Tumor-derived exosomal HOTAIRM1 can transfer into CAFs and competitively adsorb miR-328-5p, and regulate the SPON2 expression of CAFs cells, ultimately promote the progression of NSCLC." (PMID 36153414, 2022). "The expression level of HOTAIRM1 in tumours formed by sh-HOTAIRM1-transfected tMSC1 cells was lower than in the control group." (PMID 35586206, 2022). "In vivo tumorigenicity assay also showed that overexpression of HOTAIRM1 in t-FB1/2 cells led to higher tumor volume and weight, compared with the control group." (PMID 33816233, 2021). "Tumorigenicity assay indicated that HOTAIRM1 downregulation of transformed fibroblasts led to obvious decrease in both tumor volume and weight of subcutaneous implanted HOTAIRM1 knocking-down t-FB1/2 cells decreased obviously, compared with the control group." (PMID 33816233, 2021). "In vivo, the tumor growth was significantly inhibited by HOTAIRM1 knockdown, including tumor size, weight, volume, angiogenesis, and tumor hardness, as assessed by ultrasonic imaging (USI) and magnetic resonance imaging (MRI)." (PMID 35087800, 2021). "Systematic bioinformatics analyses demonstrated that HOTAIRM1 was closely related to tumor stage, overall survival, genome instability, the tumor cell stemness, the tumor microenvironment, and immunocyte infiltration." (PMID 35087800, 2021). "In vivo experiments demonstrated that HOTAIRM1 knockdown decreases tumor growth by regulating expression of the HOXA1 gene." (PMID 33807183, 2021).
tumor (continued). "HOTAIRM1 enhances the expression of HOXA1 in MDSCs and high levels of HOXA1, the target gene of HOTAIRM1, delays tumor progression and enhances the antitumor immune response by downregulating the immunosuppression of MDSCs." (PMID 34295338, 2021). "Altogether, it can be concluded that HOTAIRM1 exhibits tumorigenic properties and facilitates tumor growth in OSCC." (PMID 35087800, 2021). "In GBM, HOTAIRM1 is upregulated and promotes proliferation, migration, and invasion of tumor cells via several mechanisms." (PMID 33807183, 2021). "While, in the multivariate Cox-regression analysis, age, HOTAIRM1 expression and tumor stage were all significantly independent predictors of OS of OSCC patients." (PMID 35087800, 2021). "In summary, these findings convincingly demonstrated that HOTAIRM1-knockdown inhibited tumor growth in vivo." (PMID 35087800, 2021). "Next, we conducted an analysis to evaluate the relationship between OS and clinical data, including HOTAIRM1 expression, age, gender, tumor stage, smoking as variables." (PMID 35087800, 2021). "Overexpression of HOTAIRM1 promoted apoptosis and suppressed proliferation, invasion, and metastasis in vitro and HOTAIRM1 suppressed tumor growth in vivo." (PMID 33238475, 2020). "A newly published article has shown the anti-tumor activity of lncRNA HOTAIRM1 by up-regulation of ARHGAP24 through miR-106a-5p inhibition." (PMID 32664703, 2020). "To determine the effect of HOTAIRM1 on tumor growth, we subcutaneously injected pGBM1 cells pretransfected with sh-HOTAIRM1 into nude mice." (PMID 33323548, 2020). "It should be noted that a number of evidences have shown that HOTAIRM1 can function either as a tumor suppressor or as a tumor promoter, depending on the type of cancer." (PMID 32760219, 2020). "LncRNAs can function either as oncogenes (e.g., HOTAIR, MALAT1, H19) or as tumor suppressors (e.g., HOTAIRM1, NKILA, XIST) by targeting genes that foster or prevent tumor development and progression, respectively." (PMID 33049922, 2020). "After 7 days of the experiment, the tumor volume was measured every three days, and at each point, the Fadu cells with high expression of HOTAIRM1 obviously formed smaller tumor compared to the NC tumor." (PMID 29905017, 2018). "Taken together, these data support an important promoting role for HOTAIRM1 in GBM tumor growth in vitro and in vivo." (PMID 30376874, 2018). "Mouse tumor xenograft models were established which confirmed that overexpression of HOTAIRM1 suppressed tumor growth in vivo." (PMID 29905017, 2018). "The expression level of HOTAIRM1 in MDSCs from tumor tissues was significantly decreased compared with that in cells with the same phenotype from adjacent tissue." (PMID 29662483, 2018). "After overexpression of HOTAIRM1, cell proliferation, migration, and invasion were significantly inhibited in vitro as well as the tumor growth in vivo." (PMID 29905017, 2018). "The expressions of HOTAIRM1 and HOXA1 in GBM tissues and cells were determined by qRT-PCR, and the association between HOTAIRM1, HOXA1 transcription and tumor grade were analyzed." (PMID 30376874, 2018). "HOTAIRM1 is also reported to be a tumor suppressor by affecting a series of genes related to cell proliferation in colon cancer." (PMID 28389671, 2017). "In most patients, the level of HOTAIRM1 in tumours was significantly less than in normal tissues (P = 0.001)." (PMID 27307307, 2016). "We found HOTAIR and HOTAIRM1 were differently expressed between tumor and normal breast tissue based on our criteria." (PMID 27597120, 2016). "HOTAIRM1 has also been implicated in drug resistance in AML, potentially through the activation of glycolytic and Wnt/β-catenin signaling pathways, which influence tumor metabolism and progression." (PMID 40746924, 2025). "HOTAIRM1 exhibits dual roles as an oncogene and tumor suppressor in different solid tumors." (PMID 39553554, 2024).